ADGRG5 (adhesion G protein-coupled receptor G5)
Description:
Orphan adhesion G protein-coupled receptor (aGPCR). Ligand binding causes a conformation change that triggers signaling via guanine nucleotide-binding proteins (G proteins) and modulates the activity of downstream effectors, such as adenylate cyclase. ADGRG5 is specifically coupled to G(s) G proteins and mediates activation of adenylate cyclase activity.
Synonyms: GPR114; PGR27
Tractability: Antibody: UniProt places it where antibodies can reach, with medium confidence; UniProt predicts a signal peptide or a membrane-spanning region; its Gene Ontology location is reachable by antibodies, with medium confidence.
Target class: Family B G protein-coupled receptor; Membrane receptor
Gene: Protein-coding gene on chromosome 16 (57,542,643 to 57,591,681, forward strand). Ensembl gene ENSG00000159618.
Subcellular location: Cell membrane
Subcellular location (Human Protein Atlas): Nuclear membrane; Vesicles; Nucleoplasm
Gene Ontology:
Molecular function: G protein-coupled receptor activity; protein binding; transmembrane signaling receptor activity
Biological process: adenylate cyclase-activating G protein-coupled receptor signaling pathway; G protein-coupled receptor signaling pathway; cell surface receptor signaling pathway
Cellular component: membrane; plasma membrane
Genetic constraint (gnomAD): Loss-of-function variants: 36 observed, 48.43 expected, observed/expected ratio (o/e) 0.74, 90% interval 0.57 to 0.98. The upper end of that interval is the gene's LOEUF score, 0.98, which puts it in group 4 of 6, group 1 being the genes least tolerant of losing a copy. Missense variants: 597 observed, 641.93 expected, observed/expected ratio (o/e) 0.93, 90% interval 0.87 to 1. Synonymous variants: 267 observed, 279.04 expected, observed/expected ratio (o/e) 0.96, 90% interval 0.87 to 1.06.
Homologues: Orthologues: chimpanzee ADGRG5 (99% identical), macaque ADGRG5 (93% identical), pig ADGRG5 (72% identical), dog ADGRG5 (71% identical), guinea pig ADGRG5 (71% identical), rat Adgrg5 (71% identical), mouse Adgrg5 (70% identical). Paralogues in human: ADGRG1 (32% identical), ADGRG3 (29% identical), ADGRG2 (24% identical), ADGRG6 (24% identical), ADGRE2 (24% identical), ADGRG4 (24% identical), ADGRL3 (23% identical), ADGRL1 (23% identical), ADGRL2 (22% identical), ADGRE3 (22% identical), ADGRE5 (21% identical), ADGRE1 (20% identical), and 30 more.
Diseases named in the same sentence as ADGRG5 in open-access papers:
ADGRG5 is named in the same sentence as 5 diseases in open-access papers, as found by Europe PMC text mining. Sharing a sentence is not in itself a finding about the gene and the disease. The quoted sentences say what the papers report.
myeloma (1 paper, 2022). "There were no obvious correlations between mRNA levels of Clec9a, Riken, or Adgrg5 in osteocytes and the bone intensity in myeloma-bearing mice." (PMID 35760800, 2022). "Unsupervised hierarchical clustering of osteocytes using RNA-seq gene expression data showed a response-specific gene expression signature, including four candidates: Clec9a, Riken, Adgrg5, and Ciita that were upregulated in the osteocytes from myeloma-bearing mice." (PMID 35760800, 2022).
ADGRG5 also shares sentences with these, for which no sentence is quoted: thyroid cancer (2 papers); asthma (1); glioblastoma (1); tumor (1).